CD4 (CD4 molecule)
Diseases named in the same sentence as CD4 in open-access papers (continued):
Sharing a sentence is not in itself a finding about the gene and the disease.
melanoma (continued). "Additionally, it was recently shown that following depletion of regulatory T cells (Treg), a subset of cDC2 can effectively elicit intratumoral CD4+ T cell responses and subsequent tumor control in a mouse model of melanoma." (PMID 32508825, 2020). "Indeed, they demonstrated that SHP-2 deletion in CD4+ T cells potentiates melanoma progression and promotes metastasis in mice." (PMID 33003469, 2020). "In this study, we used an in-depth comparative transriptomic analysis of intra-melanoma DP T cells and CD4 and CD8 single positive (SP) T cells, to better comprehend the origin of this DP phenotype, and define the transcriptomic signature of activated DP T cells." (PMID 32246006, 2020). "Through the production of IL-10, melanoma cells prevent maturation of DCs, suppress production of Th1-inducing cytokine IL-12 in DCs, and inhibit their antigen-presenting properties, attenuating generation of effector CD4+Th1 and CD8+CTLs." (PMID 32695181, 2020). "In this context, a recent report found that podoplanin-expressing lymph-node stromal cells promote melanoma growth in vivo by inhibiting anti-tumor specific CD4+ T-cell proliferation and inducing the death of tumor infiltrating CD4+ lymphocytes in a cell-contact-independent fashion." (PMID 30736372, 2019). "Similarly, tumor derived MVs from both HNSCC and melanoma sera induce in vitro expansion of CD4+CD25+FoxP3+ with enhanced suppressor function." (PMID 31681327, 2019). "Further supporting the importance of neoantigen-specific CD4 T-cell responses, in a personalized vaccine trial in melanoma patients, polyfunctional CD4 T cells were observed against 60% of the 97 unique neoantigens used across patients, whereas only 16% were recognized by CD8 T cells." (PMID 31221199, 2019). "The presence of C3d on melanoma cells yields greater infiltration by CD4+ and CD8+ lymphocytes." (PMID 31031765, 2019). "Moreover, Veatch and colleagues recently identified HLA-DQB1*03-restricted BRAFV600E-specific CD4+ T cells in an acral melanoma patient, who nonetheless developed metastases under ipilimumab (anti-CTLA-4) immunotherapy." (PMID 31998317, 2019). "Uveal melanoma vaccine cells potentially present a diverse repertoire of tumor (neo)antigens restricted to HLA-DR and may therefore activate a polyclonal CD4+ T cell response." (PMID 30956760, 2019). "Similar observations were reported in murine models of renal cell carcinoma (RCC) (RENCA) and spontaneous melanoma (B16F10) where the reduced tumor growth resulted from an increased presence of CXCR3-A-expressing CD4+ and CD8+ lymphocytes and NK cells in the tumor bed." (PMID 31216755, 2019). "Interestingly, in an analysis of eight pooled cohorts including baseline samples from 190 patients with unresectable melanoma, elevated PD-L1 expression on peripheral blood CD4+ and CD8+ T cells predicted resistance to CTLA-4 blockade." (PMID 31775882, 2019). "Consequently, the peripheral and intra-tumoral expansion of CD4+/CD25+/Foxp3+ cells correlates directly with melanoma progression." (PMID 31750245, 2019). "Similarly, the importance of CD4+ cells of high concentration in hindering melanoma metastasis and recurrence has also been reported." (PMID 31608101, 2019). "As a particular finding, the data obtained this way demonstrate that broader T-cell responses with a greater diversity of CD4+ blood T-cell clones may predict longer survival of melanoma patients treated with anti-CTLA4 or PD-1 antibodies." (PMID 31275310, 2019). "CD4+ T cells may also acquire cytotoxic activity in vivo as seen in some melanomas, and can play a role in generating and maintaining memory CD8+ T cells." (PMID 31112530, 2019). "Similarly, immunization with natural HSP110 complexed with the melanoma-associated antigen gp100 protected mice against subsequent challenge with gp100-expressing B16 melanoma by bolstering both CD4+ and CD8+ T cell populations." (PMID 31695803, 2019).
melanoma (continued). "Notably, one study identified BRAFV600E-specific CD4+ T cells after repetitive peptide stimulation of peripheral blood mononuclear cells from three melanoma patients whose metastatic tumors harbored the BRAFV600E mutation." (PMID 31998317, 2019). "In addition, others identified HLA-DRB1*0401 and HLA-DP4 restricted epitopes in the carboxy-terminal end of NY-ESO-1 which can be recognized by CD4+ T lymphocytes from melanoma patients." (PMID 29770138, 2018). "The PD-1-blocking antibody pembrolizumab has been shown to elicit an increased proliferation of both, Foxp3-negative and Foxp3-positive CD4 as well as CD8 T cells in stage IV melanoma patients, displaying the most significant effects in the PD-1 expressing cells of these populations." (PMID 29032503, 2018). "We observed increased expression of PD-1 on circulating CD4+ T cells in young melanoma patients." (PMID 29546435, 2018). "Several recent studies, focusing on circulating CD4+ T cells, found that increases in central memory CD4+ T cells (CD27+, FAS−, CD45RA−, and CCR7+), and IL-9-producing CD4+ T helper (Th9) cells, correlated with good clinical responses of melanoma patients to anti-PD-1 therapy." (PMID 30073150, 2018). "This difference could be explained by a numerical decline of CD4+ T cells in melanoma patients, whereas numbers of circulating CD8+ T cells were similar in patients and controls." (PMID 29546435, 2018). "Frequent recognition of neoantigens by CD4+ T cells was also observed in human melanoma." (PMID 29403496, 2018). "The reduced activation status of circulating CD4+ T cells in old melanoma patients might contribute to the worse biological behavior and survival of melanoma in the elderly." (PMID 29546435, 2018). "Moreover, we have previously found an enrichment of CXCR3-expressing CD4+ T cells in metastatic lymph nodes compared with circulating T cells perhaps explaining the differences found in the blood between melanoma patients and healthy volunteers." (PMID 30420855, 2018). "Interestingly, proportions of CD4+ TNaive cells in young melanoma patients were comparable to those in the old patients and controls, suggesting a melanoma-induced immune response." (PMID 29546435, 2018). "They demonstrated using a B16-ova melanoma model that directly inhibiting PP2A in adoptively transferred effector CD4+ or CD8+ cells could enhance antitumor immunity." (PMID 29844427, 2018). "It would, therefore, be interesting to study CD4+ T cells in lymphoid tissues of melanoma patients." (PMID 29546435, 2018). "In advanced melanoma it was shown that a single NY-ESO-1 epitope could induce CD4+ T cell responses as well as stimulate T regulatory cells." (PMID 29770138, 2018). "This is contrary to melanoma studies in CD4 knockout mice, where protection is partially dampened." (PMID 30319653, 2018). "Moreover, it has been shown that predominant secretion of TNF by CD4+ T cells in MHC class II-expressing melanoma promotes a local immunosuppressive environment, impairing effector CD8+ T-cell functions." (PMID 29403496, 2018). "Indeed, emerging data from our group suggest that tumor-cell-intrinsic MHC II expression is dispensable for in vitro CD4+ T-cell-mediated killing in the B16 melanoma and A20 lymphoma." (PMID 30083157, 2018). "Thus, the CD4+ TNaive cell compartment of young melanoma patients resembled those of old patients and controls, rather than that of young healthy controls." (PMID 29546435, 2018). "Moreover, a recent analysis of four melanoma patients (two with stable disease, one progressive disease, and one partial response) show an increase of central memory CD4+ T cells in the two patients with longer survival times." (PMID 30123214, 2018). "It remains to be elucidated why CD4+ T cells respond poorly to melanoma in the elderly." (PMID 29546435, 2018). "However, similar to prior studies we observed recurrence of melanoma tumor in 6/6 mice receiving CD4+ T cells alone." (PMID 29481571, 2018).
melanoma (continued). "Thus, our findings suggest poor activation of peripheral CD4+ T cells in old melanoma patients, whereas the CD4+ TNaive cell pool shows signs of premature contraction in young melanoma patients." (PMID 29546435, 2018). "Likewise, tryptophan catabolism by indoleamine 2,3-dioxygenase (IDO)-producing regulatory pDC recovered from melanoma-draining lymph nodes is associated both with suppression of CD8+ T cells and with activation of CD4+ Tregs." (PMID 29209327, 2017). "Furthermore, the cryo-thermal therapy-induced durable melanoma-specific memory immune response was mainly CD4+ T-cell-dependent." (PMID 28333145, 2017). "CD26 was distributed similarly on CD4+ T cells from melanoma patients as in normal donors." (PMID 29213079, 2017). "In particular, mDC that were imprinted by ER stress in melanoma cells suppressed CD8+ T cell proliferation via secretion of the arginine-depleting enzyme arginase I, and melanoma-educated regulatory DCs have also been found to suppress CD4+ T cell proliferation in an arginase-dependent manner." (PMID 29209327, 2017). "We observed that prophylactic treatment using CBs from B16 and B16-ISAV generates a delay in tumor growth in B16 melanoma model, but only the treatment with B16-ISAV CBs showed an increase in systemic CD8+ and CD4+ lymphocytes which are associated with an antitumor response." (PMID 29062313, 2017). "However, in this melanoma solid tumor model, depleting CD4+ or CD8+ T-cells individually show a similar phenotype as the isotype depletion control." (PMID 28018602, 2016). "Moreover, melanoma cells programmed to undergo EMT can promote immune escape by generating CD4+FOXP3+ regulatory T cells and impairing dendritic cell maturation, both in vitro and in vivo." (PMID 27764776, 2016). "Moreover, neoantigen-specific CD4 T cells are commonly found among tumor-infiltrating lymphocytes in melanoma patients." (PMID 27192170, 2016). "Importantly CD4+ T cells have also been described to develop cytotoxicity and they are able to eradicate established melanomas." (PMID 25849072, 2015). "In order to assess whether inhibition of CD4+ T cell proliferation is mediated by the release of soluble factors by melanoma cells, the same experiments were performed using a transwell system." (PMID 26329660, 2015). "Therefore, employing a metastatic model of aggressive melanoma, we re-evaluated the CD4+ T-cell-mediated antitumour effects in aged mice." (PMID 25850032, 2015). "Dual staining with Annexin V-FITC and PI was employed to determine whether PBL apoptosis was induced by melanoma-derived PAEP in unfractionated PBLs or purified CD8+ or CD4+ T cells." (PMID 25785839, 2015). "To determine whether TAA-specific T cells bearing a Treg phenotype were present in the peripheral circulation of melanoma patients; we analyzed tetramer+ CD4+ T cells for co-expression of CD25hi+." (PMID 25325015, 2014). "The reasons for lack of response to IL-2 are starting to emerge: a recent study found that the T cell subset most induced by IL-2 in melanoma patients is regulatory T cells (Treg) expressing positive for CD4, CD25, Foxp3 and the inducible T cell costimulator (ICOS)." (PMID 24743024, 2014). "In studies of patients with melanoma, Fourcade and colleagues demonstrated that CD4+CD25− T cells and Foxp3+CD4+ T cells could recognize the same peptide and moreover, clonotypic analyses of these cells revealed a common T cell receptor (TCR) Vβ usage." (PMID 23874342, 2013). "Recent investigations in melanoma patients showed effectiveness of adoptive CD4+ T-cell therapy." (PMID 22890822, 2013). "Expression of Eomes in CD4+ T cells was very low in any melanoma-bearing mice." (PMID 24127404, 2013). "In either instance, more recent studies using a murine transgenic tumor model of advanced melanoma, showed that transfer of naïve tumor-reactive CD4 T cells into lymphopenic recipients can induce a substantial expansion and differentiation of Th1 cells with cytotoxic activity." (PMID 23533029, 2013).
melanoma (continued). "Additionally, in murine models of melanoma and colorectal carcinoma, the establishment of tumors has been shown to lead to increased IL-35 expression in CD4+ tumor-infiltrating lymphocytes, which are subsequently able to suppress T-cell proliferation." (PMID 24151492, 2013). "With the possible exception of melanoma, there is a distinct paucity of publications detailing the phenotypic and functional characteristics of tumor-infiltrating T cells, particularly tumor-infiltrating CD4+ T cells." (PMID 23874342, 2013). "Notably, CTLA4 blockade with ipilimumab, recently approved by FDA for the treatment of late-stage melanoma, has been shown to promote the generation of polyfunctional CD4+ T cells in response to vaccination." (PMID 22400040, 2012). "Similarly, the enlarged T cell repertoire in AIRE−/− mice enables them to mount anti-MAA and anti-melanoma responses as shown by increased anti-melanoma antibodies, and enhanced CD4+ and MAA-specific CD8+ T cell responses after melanoma challenge." (PMID 22506061, 2012). "In the current study, we utilized an expression microarray analysis of flow cytometry-purified CD4+ and CD8+ T cells to define immunologically important gene products expressed by T cells from patients with high-risk melanoma that were significantly altered after ipilimumab." (PMID 22788688, 2012). "On the other hand, naive CD4+ T cells were very recently shown to be able to differentiate into Th1 cytotoxic T cells that display the remarkable ability to eradicate on their own an established human melanoma." (PMID 22359669, 2012). "The goal of the present studies was to investigate whether CD4 T cell help is required for the generation of protective CD8 T cell memory to melanoma." (PMID 22046294, 2011). "To investigate whether apoptotic cell-loaded IFN-DC could promote the expansion of IL-17-secreting cells, we cultivated naïve CD4 T cells with autologous DC which had phagocytosed apoptotic melanoma (Me501) or cervical cancer (CaSki) cells." (PMID 21387004, 2011). "CD4 helper T cells significantly improve CD8 T cell adoptive therapy of melanoma." (PMID 22046294, 2011). "Additionally, the newly defined Treg-cell population comprises of significantly more Treg cells compared to the traditionally defined CD4+CD25high Treg cells as demonstrated recently for malignant melanoma." (PMID 21904560, 2011). "Our previous work has demonstrated that temporary depletion of CD4+CD25+ regulatory T cells (Treg) in melanoma tumor-bearing mice drives the priming of melanoma/melanocyte antigen-specific CD8 T cells that develop into protective memory following curative excision of the primary tumor." (PMID 22046294, 2011). "We could detect TRP-1284–298–specific CD4+ T cell responses also in the human system, both among healthy donors and melanoma patients." (PMID 21152437, 2010). "We found that in the B16 melanoma and the H22 hepatocarcinoma, the infiltration of CD4+ T-cells, CD8+ T-cells, CD19+ B-cells and NK1.1+ NK-cells were significantly lower in tumors containing the RBP-J deficient DCs than in the tumors containing the control SPDCs." (PMID 20420708, 2010). "Enhanced primary and recall CD8+ T cell responses like increased cell number, granule mobilization, and IFN-γ production were observed upon GITR activation during immunization with melanoma differentiation antigens, and these effects were only partially dependent on CD4+ T cells." (PMID 20936139, 2010). "Interestingly, these cells expanded robustly and importantly differentiated into cytotoxic CD4+ T cells that directly eliminated B16 melanomas." (PMID 21076522, 2010). "Similarly, the HLA-DR4-restricted peptide MART-151–73 (RNGYRALMDKSLHVGTQCALTRR) has been shown to induce high CD4+ T cell responses in conjunction with the class I peptide MART-127–35 within melanoma patients." (PMID 20016802, 2009). "Both CD4+ and CD8+ clones were melanoma reactive, but CD4+ clones dominated the cultures." (PMID 16819544, 2006).
melanoma (continued). "In the context of those findings, the results from the present study suggest that future optimization of melanoma vaccines to elicit clinically meaningful T cell responses to the vaccine may be best focused on enhancing CD4+ T cell responses to melanoma antigens." (PMID 40536492, 2025). "In murine models of melanoma, β‐emitting TRT has been shown to trigger the release of damage‐associated molecular patterns (DAMPs), promote the recruitment of immune cells—including CD4+ and CD8+ T cells, as well as NK cells —and potentially enhance tumour immunogenicity." (PMID 40898695, 2025). "To investigate whether the metabolic differences observed between male and female melanoma cells could affect the immune infiltration, we explored the role of lactate, more pronounced in male melanoma cell lines, in favouring CD4+ T cells recruitment and Treg polarisation." (PMID 39888245, 2025). "Hence, their study in unsorted scRNA-seq from patients with cancer requires specific isolation of CD4-expressing cytotoxic cells, which was done in reanalysis of published data to provide evidence for cytotoxic CD4+ T cells in breast cancer, head and neck cancer, melanoma, and liver cancer." (PMID 40299576, 2025). "Our results indicated that ZDHHC13 in B16 cells notably increased the proportion of M1-like TAMs, CD8+, CD4+, and NK cells, while diminishing the population of M2-like TAMs in subcutaneously inoculated tumors as well as in tail vain injection–induced melanoma lung metastasis." (PMID 41321310, 2025). "Indeed, IL-36α over-expression increased the recruitment of MHC IIhigh macrophages and CD8+ T lymphocytes and decreased the infiltration of regulatory T cells, CD4+ T cells, and monocytic myeloid-derived suppressor cells (M-MDSCs) in the melanoma microenvironment." (PMID 39126091, 2024). "Importantly, cytotoxic CD8+ T cells versus CD4+Foxp3+ regulatory T cells ratio may have predictive value for melanoma outcome." (PMID 38920557, 2024). "Furthermore, the same group demonstrated that NAFLD/NASH-associated steatohepatitis reduced the ability of immunotherapeutic agents to inhibit intrahepatic transplanted melanoma or colon cancer tumor growth by reducing the number of tumor-infiltrating CD4+T cells." (PMID 39000005, 2024). "Local delivery of MPN/CpG effectively inhibits tumor growth in a B16 melanoma‐bearing mouse model, reshaping the tumor microenvironment (TME) by repolarizing M2‐type tumor‐associated macrophages (TAMs) to an M1‐type and boosting intra‐tumoral infiltration of CD8+/CD4+ T lymphocytes and DCs." (PMID 39258810, 2024). "We found that training CellSighter on the melanoma lymph node data and evaluating on the gastrointestinal data achieves high results for major cell types that shared all of their defining proteins, including CD4 T cells (88%), Tregs (83%), CD8 T cells (93%) and Endothelial cells (82%)." (PMID 37463931, 2023). "Another study has shown that a rejection of subcutaneous melanoma tumors following intra-tumoral injection of IFNβ-expressing insect cells inhibits subsequent colonization of the brain by the same melanoma cell line, and depletion of CD4+ and CD8+ T cells abrogated this effect." (PMID 38567052, 2023). "Therefore, in TERT-high hypoxic melanoma, dysfunctional CD4+ T cells may accumulate employing these immuno-suppressive checkpoints." (PMID 37418389, 2023). "In addition, our data indicate dysfunctional CD4+ T cells in TERT high hypoxic melanoma." (PMID 37418389, 2023). "In contrast, BrM from melanoma have higher presence of CD4 and CD8 positive T cells, while BrM in breast cancer has a higher presence of neutrophils and macrophages, indicating that breast cancer BrM may show increased drug resistance compared with melanoma BrM." (PMID 37056723, 2023).